BTLA (B and T lymphocyte associated)
Diseases named in the same sentence as BTLA in open-access papers (continued):
Sharing a sentence is not in itself a finding about the gene and the disease.
autoimmune disease (33 papers, 2011 to 2025). A disorder resulting from loss of function or tissue destruction of an organ or multiple organs, arising from humoral or cellular immune responses of the individual to their own tissue constituents. "Although BTLA expression has been seen on non-haematopoietic cells in some settings, these data indicated that loss of BTLA in foetal liver derived cells alone was sufficient for the generation of multi-organ autoimmune disease in the recipients." (PMID 39471840, 2024). "To examine in more detail the autoimmune disease generating effects of BTLA deficiency in newly generated versus established Btla−/− T cells, we compared transfers of FLC, thymocytes, whole splenocytes or sorted splenic T cells to syngeneic Rag−/− recipients." (PMID 39471840, 2024). "BTLA deficient mice were shown to have higher T-cell activity and increased vulnerability towards autoimmune diseases." (PMID 38928307, 2024). "Mice deficient in BTLA develop autoimmune disease only later in life, suggesting that either other co-inhibitors compensate for the loss of BTLA in early life, or early events take time for their consequences to become apparent." (PMID 39471840, 2024). "We found that loss of BTLA or PD-1 post-thymic selection in RTE resulted in autoimmune disease in lymphopenic host mice, associated with loss of weight, dermatitis, diarrhoea and T cell infiltration of organs." (PMID 39471840, 2024). "Blockade of BTLA in T-cells increased T-cell proliferation, and BTLA deficient mice display increased incidence and severity of autoimmune diseases, such as EAE." (PMID 36159789, 2022). "Reports continue to emerge linking BTLA polymorphisms to autoimmune disease, development of cancer, or viral infection." (PMID 35320716, 2022). "Accumulating evidence indicates that co-inhibitory molecules, such as CTLA-4, PD1, and BTLA, are negative regulators of immune responses since deficiencies or mutations result in the development of autoimmune diseases." (PMID 27965674, 2016). "Consistent with a proposed role as an inhibitory co-signaling receptor, BTLA-deficient T cells show increased proliferation, and BTLA-knockout mice have enhanced susceptibility to autoimmune disease and increased inflammatory responses." (PMID 24205056, 2013). "We, therefore, attempted to identify SNPs in the human BTLA gene in the Japanese population and investigated its association with susceptibility to autoimmune diseases." (PMID 21403914, 2011). "Therefore, BTLA deficiencies in various experimental animal models promote the development of autoimmune diseases or worsen their course." (PMID 38279272, 2024). "The first evidence for the inhibitory function of BTLA was demonstrated in mice deficient for this receptor, which showed an augmented risk of developing autoimmune diseases, such as encephalomyelitis and whose T lymphocytes displayed increased proliferative capacity as well." (PMID 37649037, 2023). "BTLA deficient mice have fewer Tregs and develop autoimmune diseases such as EAE." (PMID 36159789, 2022). "Studies regarding the genetic variations of BTLA have mainly focused on its role in cancer (for example, lymphocytic leukemia and breast cancer) and susceptibility to autoimmune diseases (for example, rheumatoid arthritis, systemic lupus erythematosus and type 1 diabetes mellitus)." (PMID 29245962, 2017). "Despite the important role of BTLA in maintaining immune homeostasis, relatively little studies were devoted to the relationship of polymorphisms in the gene encoding BTLA with susceptibility to autoimmune disease and cancer." (PMID 25182981, 2015). "To determine whether #590 and #800 SNPs of BTLA gene are involved in the susceptibility to autoimmune diseases, we first established a method that distinguishes homozygous and heterozygous genotypes of these SNPs." (PMID 21403914, 2011).
autoimmune disease (continued). "We have recently identified B and T lymphocyte attenuator (BTLA), a new inhibitory coreceptor expressed on immune cells, and we suggest that BTLA may be involved in the development of autoimmune diseases using BTLA-deficient mice." (PMID 21403914, 2011). "Thus, we focused on #590 and #800 SNPs of BTLA gene to determine whether these SNPs are associated with susceptibility to autoimmune diseases." (PMID 21403914, 2011). "Its structure makes BTLA a crucial immune system regulator, and its function can be modulated in the context of cancer immunotherapy and autoimmune disease treatments." (PMID 40574024, 2025). "Conversely, reduced BTLA expression in autoimmune diseases contributes to excessive lymphocyte activation and tissue damage within the body." (PMID 40574024, 2025). "The role of BTLA engagement by HVEM in the pathogenesis of autoimmune diseases has recently gained attention." (PMID 41373483, 2025). "Studies have shown that BTLA expression is often reduced in patients with severe asthma or autoimmune diseases." (PMID 40226621, 2025). "BTLA is thus a key regulator of the immune response, whose expression and function can be modulated to treat both cancer and autoimmune diseases." (PMID 40574024, 2025). "Still, the therapeutic advantages of targeting BTLA or HVEM deserve further consideration in the context of cancer or autoimmune diseases, where this axis is often dysregulated." (PMID 37649037, 2023). "Intense research in the field of cancer, autoimmune diseases and various infection has revealed the interaction of BTLA with its ligand HVEM has a potent inhibitory effect on adaptive, majorly T-cell mediated, immune response." (PMID 35701741, 2022). "BTLA is an essential immune checkpoint molecule in regard to autoimmune diseases, infections, and cancer." (PMID 36741370, 2022). "BTLA functions as an inhibitory receptor that dampens immune responses and BTLA-/- mice show increased autoimmune diseases and allergic airway inflammation, as well as deficits in tolerance induction and T cell homeostasis." (PMID 36081508, 2022). "A next-generation therapeutic mode is the activation of inhibitory receptors like BTLA to treat autoimmune disease." (PMID 35320716, 2022). "Recently, a large number of studies have found that BTLA participates in numerous physiopathological processes, such as tumor, inflammatory diseases, autoimmune diseases, infectious diseases, and transplantation rejection." (PMID 33859648, 2021). "For instance, several studies using animal models of autoimmune diseases proved the involvement of HVEM/CD160/BTLA/LIGHT pathway in the development of autoimmune diseases." (PMID 30842773, 2019). "Novel molecules like BTLA+ are also pivotal for T-cell regulation and activation, especially in autoimmune diseases." (PMID 31514450, 2019). "There is substantial evidence that suggests disorder of the HVEM/LIGHT/BTLA/CD160 signaling system is essential in the development of autoimmune diseases and allograft rejection." (PMID 29245962, 2017). "Based on published studies in autoimmune disease models we anticipated that VACV-specific BTLA−/− CD8 T cells would have augmented responses." (PMID 24205056, 2013). "However, co-inhibitory molecules such as CTLA-4, PD-1 and BTLA have been shown to be crucial for the prevention of autoimmunity and polymorphism or deficiency of these molecules are associated with genetic susceptibility to autoimmune diseases in human and mice." (PMID 23829304, 2013). "We have also shown that BTLA plays a protective role in autoimmune diseases in MRL-lpr mice and that AIH-like disease develops in BTLA-deficient mice even in the absence of Fas-dependent signaling." (PMID 22997525, 2012). "Understanding the mechanisms regulating BTLA expression may be essential for developing new therapeutic strategies in oncology and treatment of autoimmune diseases." (PMID 40574024, 2025).
autoimmune disease (continued). "Additionally, TNFRSF14 interacts with BTLA to balance immune activation and suppression, which is of great significance in autoimmune diseases and tumor immune evasion." (PMID 41157169, 2025). "Whether BTLA signalling is needed in conventional and/or Treg cells to prevent the multi-organ autoimmune disease will require further studies." (PMID 39471840, 2024). "The role of BTLA as a negative co-stimulatory receptor has been substantiated by studying mice lacking BTLA, which displayed increased susceptibility to autoimmune disorders." (PMID 38279272, 2024). "There is evidence from animal studies that BTLA knockout leads to autoimmune diseases." (PMID 31921121, 2019). "However, BTLA as a co-inhibitor is scarcely studied in human autoimmune diseases and its role in disease pathogenesis is unclear." (PMID 31921121, 2019). "Deficiency of BTLA-HVEM interaction has been shown to be involved in autoimmune diseases, though no clinical trial is yet in progress." (PMID 27965674, 2016). "Mice lacking BTLA or HVEM show increased susceptibility to autoimmune diseases but improved immune responses to some infectious agents confirming that BTLA and HVEM have immunoinhibitory functions." (PMID 27922818, 2016). "We assume that the enhancement of BTLA signaling is applicable to the treatment of autoimmune diseases and that the blockade of this pathway may be useful for the treatment of the reduced immune responses against tumors or infection." (PMID 22997525, 2012). "Interestingly, adult mouse splenic T cells from mice with germline BTLA or PD-1 deficiency did not cause overt autoimmune diseases in the recipients." (PMID 39471840, 2024). "However, BTLA as a co-inhibitor is scarcely studied in human autoimmune diseases and its role in disease pathogenesis of SLE remains unclear." (PMID 31514450, 2019). "In this study, we aimed to understand the relationship between the constitutively expressed T cell co-inhibitory molecules BTLA and CD5, and an induced co-inhibitor, PD-1, in the steady state and under conditions that promote multi-organ autoimmune disease." (PMID 39471840, 2024). "Since BTLA plays a significant role in maintaining self-tolerance, BTLA-HVEM pathway disturbance has been demonstrated to be involved in the pathogenesis of autoimmune diseases, infections, and cancer." (PMID 36741370, 2022). "Since the discovery of BTLA in 2003, multiple studies have established that the HVEM-BTLA signaling pathway plays an essential immunomodulatory role in autoimmune disease, cancer, transplantation, infection, and other diseases." (PMID 30984188, 2019). "However, the role of BTLA in the pathogenesis of autoimmune diseases in humans remains unknown." (PMID 21403914, 2011). "B- and T-lymphocyte attenuator (BTLA), a type I membrane protein belonging to the Ig superfamily that acts as a co-inhibitory receptor, is possibly involved in the pathogenesis of autoimmune diseases." (PMID 41373483, 2025). "BTLA plays an important role in the maintenance of T cell tolerance, as disturbances of the BTLA-HVEM pathway have been shown to be involved in the pathogenesis of neoplastic disorders, infections, and autoimmune diseases." (PMID 32775467, 2020). "Additionally, the aberrantly expression of HVEM, BTLA, and LIGHT has been studied in some autoimmune diseases, such as RA, T1DM, and SLE, and there was disease-specific difference in the outcomes." (PMID 30842773, 2019). "RTE lacking BTLA caused a CD4 T cell and MHC class II dependent multi-organ autoimmune disease." (PMID 39471840, 2024). "Collectively, these data demonstrated a requirement for BTLA in newly generated T cells to establish tolerance and prevent lymphopaenia-potentiated autoimmune disease, while BTLA was not required for maintaining tolerance of established T cells under these conditions." (PMID 39471840, 2024).
breast cancer (21 papers, 2011 to 2025). A primary or metastatic malignant neoplasm involving the breast. "In one of the first works on BTLA SNPs in cancer, Fu’s group reported that rs1844089[CT] and rs2705535[CT] genotypes increased the risk of breast cancer while rs1844089 [CC], rs2705535[CC] and rs9288952 [GG] genotypes decreased its risk." (PMID 36741370, 2022). "Our previous research showed that BTLA polymorphisms were associated with the risk of breast cancer." (PMID 23976978, 2013). "Previous studies showed that SNPs of Cytotoxic T lymphocyte antigen -4 (CTLA-4) and B and T lymphocyte attenuator (BTLA) might confer susceptibility to breast cancer, which suggests the critical role of costimulatory molecules in the development of breast cancer." (PMID 21917182, 2011). "Evidence has also indicated that targeting BTLA (or HVEM) is a very promising novel immunotherapy for breast cancer treatment." (PMID 36765782, 2023). "Herpesvirus entry mediator (HVEM), which is widely expressed in various cell types (including in breast cancer) and participates in immune homeostasis, is the ligand of BTLA." (PMID 36765782, 2023). "BTLA is highly expressed in type I NKT cells in murine autochthonous mammary tumors, and BTLA-neutralizing antibodies can inhibit tumor proliferation and pulmonary metastasis." (PMID 33859648, 2021). "We observed dominant expression of B- and T-lymphocyte attenuator (BTLA) on type I NKT cells in polyoma middle T oncogene-driven (PyMT) murine autochthonous mammary tumors." (PMID 29518903, 2018). "Overall, these data suggest a possible role for BTLA in survival of patients with mammary carcinoma, at least under conditions of high innate-like lymphocyte infiltration." (PMID 29518903, 2018). "We propose a major role for NKT cells in our model, since these cells selectively expressed high BTLA levels in PyMT mammary carcinoma." (PMID 29518903, 2018). "Significance of this analysis is exemplified by the fact that mutations of BTLA, CD28, CD4, and CD8A genes in the GO term cell surface receptor-linked signal transduction contribute to sporadic breast cancer risk." (PMID 27911271, 2017). "Some SNPs in six immunological genes, BTLA, ITGAL, CTLA4, ICOS, PDCD1, and VTCN1 were reported as breast cancer risk mutations in previous studies." (PMID 27911271, 2017). "Additionally, Sekar’s group explored the METABRIC dataset to analyze BTLA expression in patients with mammary cancer." (PMID 38233898, 2024). "Furthermore, in certain cancer types like gastric and breast cancer, elevated BTLA levels correlate with poor prognosis, suggesting its role as a prognostic marker." (PMID 38233898, 2024). "Moreover, it was shown on mice models of breast cancer that blocking of BTLA pathway promotes the anticancer activity of NKT cells, which infiltrate tumors and inhibit tumor growth." (PMID 33519815, 2020). "Thus, it remains to be determined which innate lymphocyte subset produces the anti-BTLA effect in mice, and which cellular subset mediates the association of ZBTB16 with patient survival in human mammary carcinoma." (PMID 29518903, 2018). "In this study, we therefore analyzed the expression of immune checkpoint receptors PD-1 and BTLA on NKT cells in a model of mammary carcinoma and explored the potential of downregulating BTLA expression on type I NKT cells and the consequences in tumor progression and the propagation of metastasis." (PMID 29518903, 2018). "Thus, miR-149-3p may also be applied in breast cancer immunotherapy via regulating the expression of PD-1, TIM-3, and BTLA." (PMID 36765782, 2023). "Additionally, in mouse models of breast cancer, type I NKT cells express high levels of BTLA, and blocking the BTLA signaling pathway may promote infiltration of tumors by NKT cells and inhibit tumor growth." (PMID 30984188, 2019).
lung cancer (20 papers, 2013 to 2025). A malignant neoplasm involving the lung. "To date, the association of BTLA polymorphisms with lung cancer susceptibility has been studied in Caucasian, Tunisian and Chinese populations." (PMID 38233898, 2024). "In an immunohistochemical analysis in human lung cancer samples, an association of BTLA expression, shorter survival and lymphatic invasion was found." (PMID 38928307, 2024). "The association between BTLA SNPs and lung cancer susceptibility has been studied previously in Chinese population (rs1982809, rs16859629, rs2171513, rs3112270) and Tunisian population (rs1982809, rs9288953, rs9288952)." (PMID 36741370, 2022). "BTLA rs1982809 AG genotype carriers had a higher risk of developing lung cancer when compared to AA genotype carriers in Tunisian population." (PMID 34163466, 2021). "A pharmacogenetic study suggested that a BTLA polymorphism with potential function to modify miRNA binding sites (rs76844316) was connected to the occurrence and prognosis of lung cancer." (PMID 34163466, 2021). "The association of the following genetic variants of BTLA rs1982809A>G, rs9288952A>G and rs9288953C>T with lung cancer risk was studied recently in the Tunisian population (196 patients, 300 controls)." (PMID 33519815, 2020). "Through subgroup analysis, we found that BTLA rs1982809 polymorphism might contribute to cancers in Caucasians, and rs1982809 polymorphism might be a risk factor for lung cancer." (PMID 35945755, 2022). "All in all, our study is significantly meaningful, we found that rs1982809 polymorphism in BTLA may be a risk factor for cancer, especially in Caucasians, and this SNP might contribute to lung cancer." (PMID 35945755, 2022). "A high expression of BTLA in different types of cancers (e.g., colorectal cancer, melanoma cancer, and lung cancer) was found to inhibit the expression and function of T-cells." (PMID 35127742, 2021). "With regard to age, gender, smoking status, and metastases status statistical analysis failed to reveal any association of BTLA SNPs with lung cancer risk." (PMID 38233898, 2024). "Studies have determined that SFTPC is overexpressed in long-term surviving NSCLC patients, indicating its potential as a biomarker for lung cancer treatment.Furthermore, activation of the BTLA/HVEM pathway is regarded as the initiator of immune escape in lung cancer." (PMID 37187731, 2023). "BTLA plays an important role in immunoregulation and is involved in the pathogenesis of various respiratory diseases, including airway inflammation, asthma, infection, pneumonia, acute respiratory distress syndrome and lung cancer." (PMID 34163466, 2021). "A research in mice that received subcutaneous implantation of lung cancer cells showed that the expression of BTLA on CD4+ T cells and CD8+ T cells increased and the number of these T cells increased as well, while BTLA+/CD8+ T cells produced less IL-2 and TNF." (PMID 34163466, 2021). "Moreover, we evaluated the BTLA expression by flow cytometry and the results showed that BTLA was expressed in a subpopulation (BTLA positively ranged from 1.97% to 7.55% in lung cancer cell lines)." (PMID 36552785, 2022). "Although, it can be postulated that BTLA rs1982809*T allele may confer increased susceptibility to cancer development, the published already data indicated that C allele confers susceptibility to several cancers (CLL, renal and lung cancer)." (PMID 33519815, 2020). "demonstrate that BTLA, along with markers like PD-1 and TIM-3, is upregulated in T cells post-tumor implantation in mice and in infiltrating CD8 T cells in advanced lung cancer patients, underscoring its role in T cell dysfunction during tumor progression." (PMID 39726592, 2024). "The expression of BTLA was increased in the CD4+ and CD8+ T cells of pleural fluid of patients with lung cancer." (PMID 34163466, 2021). "Clinical trials of immune checkpoint modulators (TIM3, LAG-3, TIGIT, BTLA, and IDO) in lung cancer." (PMID 39726592, 2024).